IGDCC4 (immunoglobulin superfamily DCC subclass member 4)
Synonyms: DDM36; NOPE; LOC57722
Tractability: Antibody: UniProt places it where antibodies can reach, with high confidence; UniProt predicts a signal peptide or a membrane-spanning region; its Gene Ontology location is reachable by antibodies, with medium confidence. PROTAC: its protein half-life has been measured.
Gene: Protein-coding gene on chromosome 15 (65,381,479 to 65,423,083, reverse strand). Ensembl gene ENSG00000103742.
Subcellular location: Cell membrane
Subcellular location (Human Protein Atlas): Cytosol; Nucleoplasm
Gene Ontology:
Molecular function: protein binding
Biological process: cell-cell adhesion; negative regulation of neurogenesis
Cellular component: plasma membrane
Genetic constraint (gnomAD): Loss-of-function variants: 71 observed, 106.96 expected, observed/expected ratio (o/e) 0.66, 90% interval 0.55 to 0.81. The upper end of that interval is the gene's LOEUF score, 0.81, which puts it in group 3 of 6, group 1 being the genes least tolerant of losing a copy. Missense variants: 1,487 observed, 1,525.9 expected, observed/expected ratio (o/e) 0.97, 90% interval 0.93 to 1.02. Synonymous variants: 700 observed, 652.57 expected, observed/expected ratio (o/e) 1.07, 90% interval 1.01 to 1.14.
Homologues: Orthologues: chimpanzee IGDCC4 (99% identical), macaque IGDCC4 (97% identical), dog IGDCC4 (90% identical), pig IGDCC4 (90% identical), rabbit IGDCC4 (89% identical), mouse Igdcc4 (88% identical), rat Igdcc4 (88% identical), guinea pig IGDCC4 (85% identical), zebrafish igdcc4 (48% identical). Paralogues in human: PRTG (33% identical), IGDCC3 (24% identical), DCC (21% identical), NEO1 (21% identical), SDK2 (20% identical), SDK1 (20% identical), ROBO1 (20% identical), ROBO2 (20% identical), CDON (19% identical), ROBO3 (19% identical), BOC (17% identical), CNTN2 (16% identical), and 24 more.
Diseases named in the same sentence as IGDCC4 in open-access papers:
IGDCC4 is named in the same sentence as 6 diseases in open-access papers, as found by Europe PMC text mining. Sharing a sentence is not in itself a finding about the gene and the disease. The quoted sentences say what the papers report.
hepatocellular carcinoma (2 papers, 2021 to 2022). A malignant tumor that arises from hepatocytes. "Regarding Igdcc4, also described as being involved in immune response and a biomarker in hepatocellular carcinoma, further studies should investigate its precise role in microglia." (PMID 33968923, 2021).
virus infection (1 paper, 2021). "We investigated the cellular distribution of IGDCC4 and viral NP protein at the early stage of virus infection by using confocal fluorescent microscopy." (PMID 34871331, 2021).
tumor (3 papers, 2015 to 2021). "For instance, mutations in the IGDCC4, ARHGEF18, MAP2K3 or AIF1L genes, which were observed in fractions exceeding 80% in the primary tumor ranged from 0 to 86% in the PDXs or secondary nodules." (PMID 26334103, 2015). "A pervious study has identified IGDCC4 as a novel oncofetal surface marker for murine and human HCC and it is specifically expressed by epithelial tumor cells but not in preneoplastic stages and is a promising marker." (PMID 29301256, 2018).
infection (2 papers, 2021). The state of being infected such as from the introduction of a foreign agent such as serum, vaccine, antigenic substance or organism. "Half of the IGDCC4-knockout mice survived a lethal H5N1 virus challenge, whereas all of the wild-type mice died within 11 days of infection." (PMID 34871331, 2021).
cancer (1 paper, 2021). A tumor composed of atypical neoplastic, often pleomorphic cells that invade other tissues. "Further research is required to fully establish the contribution of each specific gene, including four outstanding genes (Slc41a3, Fabp5, Mthfd1l and Igdcc4) with clinical relevance in human cancer." (PMID 33917315, 2021).
IGDCC4 also shares sentences with these, for which no sentence is quoted: esophageal adenocarcinoma (1 paper).